KIAA1614 (KIAA1614)
Tractability: No criterion of Open Targets' tractability assessment is met for any kind of drug.
Gene: Protein-coding gene on chromosome 1 (180,912,897 to 180,951,614, forward strand). Ensembl gene ENSG00000135835.
Subcellular location (Human Protein Atlas): Nuclear membrane; Vesicles
Gene Ontology:
Biological process: centrosome cycle; establishment or maintenance of cell polarity; regulation of cellular localization
Cellular component: apical plasma membrane; cell cortex; nucleus
Genetic constraint (gnomAD): Loss-of-function variants: 76 observed, 82.26 expected, observed/expected ratio (o/e) 0.92, 90% interval 0.77 to 1.12. The upper end of that interval is the gene's LOEUF score, 1.12, which puts it in group 4 of 6, group 1 being the genes least tolerant of losing a copy. Missense variants: 1,528 observed, 1,508.7 expected, observed/expected ratio (o/e) 1.01, 90% interval 0.97 to 1.06. Synonymous variants: 706 observed, 655.78 expected, observed/expected ratio (o/e) 1.08, 90% interval 1.01 to 1.15.
Homologues: Orthologues: chimpanzee KIAA1614 (98% identical), macaque KIAA1614 (90% identical), dog KIAA1614 (63% identical), pig KIAA1614 (62% identical), guinea pig KIAA1614 (57% identical), mouse BC034090 (56% identical), rat Kiaa1614 (56% identical), rabbit KIAA1614 (50% identical), zebrafish si:dkey-121a11.3 (22% identical), tropical clawed frog KIAA1614 (22% identical), zebrafish si:ch211-13f8.1 (16% identical). Paralogues in human: SYNJ2BP (3% identical), COX16 (2% identical).
Diseases named in the same sentence as KIAA1614 in open-access papers:
KIAA1614 is named in the same sentence as 12 diseases in open-access papers, as found by Europe PMC text mining. Sharing a sentence is not in itself a finding about the gene and the disease. The quoted sentences say what the papers report.
COVID-19 (2 papers, 2022 to 2024). A disease caused by infection with severe acute respiratory syndrome coronavirus 2. "As a result, it is safe to conclude that the five genes, ABCB6, KIAA1614, MND1, RIPK3, and SMG1, are truly COVID-19 specific, and the newly proposed classification method is a powerful tool." (PMID 35632517, 2022).
glioma (1 paper, 2024). A benign or malignant brain and spinal cord tumor that arises from glial cells (astrocytes, oligodendrocytes, ependymal cells). "Furthermore, we could identify several novel glioma biomarkers likely helpful in both diagnosis and prognosis of the patients, including the genes PPP1R8, GPBP1L1, KIAA1614, C14orf23, CCDC77, BVES, EXD3, CD300A, and HEPN1." (PMID 38812741, 2024). "For instance, the methylation of the gene KIAA1614 is a potential biomarker with both diagnosis and prognosis value in GBM, yet its function is still not elucidated in glioma." (PMID 38812741, 2024).
hyperlipidemia (1 paper, 2022). "Analysis of upregulated DEGs has shown that the following seven genes were common between all complications of TIDM (hyperlipidemia, neuropathy, ketoacidosis, hypothyroidism and PCOS): SPINK9, TRDN, PVRL4, MYO3A, PDLIM1, KIAA1614 and GRP." (PMID 36175575, 2022).
neuropathy (1 paper, 2022). A disorder affecting the nervous system that manifests with pain, tingling, numbness, and/or muscle weakness. "As shown in Boxplots 8A and 8B, KIAA1614 and TRDN were significantly upregulated in neuropathy (p < 0.05)." (PMID 36175575, 2022).
tumor (2 papers, 2018 to 2025). "Low p-values (as in the genes KIAA1614 and MRC2) indicate a significant form of silencing or activation of the genes by methylation that can lead to tumor behavior and prognosis." (PMID 41300918, 2025).
cancer (1 paper, 2024). A tumor composed of atypical neoplastic, often pleomorphic cells that invade other tissues. "The L3MBTL3, PLA2G7, KIAA1614, and C3orf33 genes were implicated in DNA repair, cell proliferation, apoptosis, and the cell cycle, and may be involved in the development of cancers." (PMID 39839768, 2024).
KIAA1614 also shares sentences with these, for which no sentence is quoted: breast carcinoma (1 paper); colon cancer (1); hypothyroidism (1); pancreatic cancer (1); prion disease (1); ulcerative colitis (1).